PNMA2 (PNMA family member 2)
Synonyms: MA2; RGAG2; MM2
Tractability: PROTAC: ubiquitination databases record sites on it; its protein half-life has been measured.
Gene: Protein-coding gene on chromosome 8 (26,504,701 to 26,514,092, reverse strand). Ensembl gene ENSG00000240694.
Subcellular location: Nucleus, nucleolus
Gene Ontology:
Molecular function: protein binding
Biological process: positive regulation of apoptotic process
Cellular component: nucleolus
Genetic constraint (gnomAD): Loss-of-function variants: 11 observed, 15.01 expected, observed/expected ratio (o/e) 0.73, 90% interval 0.46 to 1.21. The upper end of that interval is the gene's LOEUF score, 1.21, which puts it in group 5 of 6, group 1 being the genes least tolerant of losing a copy. Missense variants: 455 observed, 474.73 expected, observed/expected ratio (o/e) 0.96, 90% interval 0.89 to 1.04. Synonymous variants: 175 observed, 195.04 expected, observed/expected ratio (o/e) 0.9, 90% interval 0.79 to 1.02.
Homologues: Orthologues: chimpanzee PNMA2 (99% identical), macaque PNMA2 (97% identical), dog PNMA2 (90% identical), pig PNMA2 (90% identical), rat Pnma2 (79% identical), mouse Pnma2 (78% identical). Paralogues in human: PNMA3 (48% identical), PNMA1 (47% identical), PNMA5 (45% identical), MOAP1 (44% identical), PNMA6A (41% identical), PNMA6E (38% identical), PNMA6F (36% identical), PNMA8A (25% identical), ZCCHC18 (24% identical), ZCCHC12 (23% identical), PNMA8B (20% identical), CCDC8 (18% identical), and 1 more.
Diseases named in the same sentence as PNMA2 in open-access papers:
PNMA2 is named in the same sentence as 107 diseases in open-access papers, as found by Europe PMC text mining. Sharing a sentence is not in itself a finding about the gene and the disease. The quoted sentences say what the papers report.
encephalitis (36 papers, 2007 to 2026). An acute inflammatory process affecting the brain parenchyma. "Down-regulation of PNMA2, whose product is a target of neurodegenerative autoimmune responses, is reminiscent of a PNMA2-autoantibody-associated encephalitis patient with ALS symptoms, who presented with inflammation in cortex and spinal-cord grey matter." (PMID 17244347, 2007). "It is easy to explain that the more parts of the cerebral cortex involved, the worse the ability to recover function, as seen in our anti-NMDAR and anti-PNMA2 + /Ma2/Ta patients who developed encephalitis." (PMID 37986052, 2023). "Similarly, the association between Pnma2 (MGI:2444129, ENTREZ:10687) and encephalitis (HP:0002383) is not included in either MGI or the HPO database although recent evidence suggests such an involvement (PMID:27003254)." (PMID 30809638, 2019).
paraneoplastic neurological syndromes (15 papers, 2008 to 2026). "PNMA2, primarily expressed in the brain, is associated with paraneoplastic neurological syndromes, often accompanying peripheral solid tumors." (PMID 38962317, 2024).
germ cell tumor (7 papers, 2019 to 2025). A benign or malignant, gonadal or extragonadal neoplasm that originates from germ cells. "Six patients (24.0%) had tumors or evidence of malignancy with two patients presented with high blood level of CA-125 (anti-Yo, PNMA2) and the other four patients each presented with germ cell tumor (anti-Yo), ovarian tumor (anti-CV2), neuroblastoma (anti-GAD) and pancreatic cancer (PNMA2)." (PMID 31694559, 2019).
autoimmune disease (2 papers, 2020 to 2024). A disorder resulting from loss of function or tissue destruction of an organ or multiple organs, arising from humoral or cellular immune responses of the individual to their own tissue constituents. "With the discovery of antibodies to onconeural intracellular antigens, such as Hu, PNMA2 (Ma2/Ta) and CV2/CRMP5, LE has been recognized as an autoimmune disease." (PMID 31900128, 2020).
lung adenocarcinoma (2 papers, 2013 to 2020). A carcinoma that arises from the lung and is characterized by the presence of malignant glandular epithelial cells. "Finally, to examine the relationship between lncRNA perturbators and lncRNA-perturbated mRNAs, we overexpressed lncRNA SNHG7 and TUG1 in the A549 lung adenocarcinoma cell line and experimentally validated their function to remarkably enhance the expression of PNMA2 and CDC7 respectively." (PMID 32846981, 2020).
Achalasia (1 paper, 2018). A disorder of esophageal motility characterized by the inability of the lower esophageal sphincter to relax during swallowing and by inadequate or lacking peristalsis in the lower half of the body of the esophagus. "Additionally, we documented achalasia-associated autoantigens PNMA2, Ri, GAD65, and VIP as novel MMP-9 substrates." (PMID 30449890, 2018).
endometriosis (1 paper, 2025). The growth of functional endometrial tissue in anatomic sites outside the uterine body. "The Ciberort algorithm was employed to discern the association between PNMA2 gene expression and more than 20 distinct immune cell infiltration types in endometriosis." (PMID 40323214, 2025). "The aim of this study was to investigate the expression, function, regulatory mechanism, and relationship with immune cell infiltration of PNMA2 in endometriosis." (PMID 40323214, 2025). "This study investigates the potential involvement and regulatory mechanisms of PNMA2 in the development of endometriosis through the integration of public data, machine learning, clinical sample transcriptome sequencing, and in vitro cell experiments." (PMID 40323214, 2025). "The expression of PNMA2 exhibited a notable increase in individuals with endometriosis." (PMID 40323214, 2025).
glaucoma (1 paper, 2020). Increased pressure in the eyeball due to obstruction of the outflow of aqueous humor. "The PNMA2 protein seems to be prone to an autoimmune reaction, which could also be relevant to other neurodegenerative diseases such as glaucoma." (PMID 32140226, 2020). "Therefore, we wanted to evaluate whether validated glaucoma‐related AAbs to PNMA2, TARS, C1QBP and HSPD1 hold the potential to serve as biomarker candidates." (PMID 32140226, 2020). "Bioinformatic analysis of POAG‐related autoantigens showed a strong association with the PDGFRB pathway and also increased levels of PNMA2, TARS, and C1QBP autoantibodies in the serum of POAG patients as potential glaucoma biomarkers." (PMID 32140226, 2020). "While antibodies to HSPD1 (mitochondrial 60 kDa heat shock protein) have frequently been observed in association with glaucoma, AAbs to C1QBP, TARS and PNMA2 have not yet been described in the disease context." (PMID 32140226, 2020). "Lastly, we could confirm the presence of increased levels of AAbs against PNMA2, TARS and C1QBP in the serum of POAG patients that deserve to be further analysed as potential glaucoma biomarkers." (PMID 32140226, 2020).
serous ovarian cancer (1 paper, 2021). "In the serous ovarian cancer patients of cohort 2 (n = 20/80), detectable antibodies (Z-scores > 0) were seen against CTAG2 (n = 3/20, 15%), SHARPIN (n = 2/20, 10%), PNMA2 (n = 2/20, 10%), MAGEB4 (n = 1/20, 5%), MRFAP1L1 (n = 1/20, 5%), SERPINB1 (n = 1/20, 5%) and XAGE3 (n = 1/20, 5%)." (PMID 34681879, 2021).
small intestine carcinoid tumors (1 paper, 2023). "The field continues to search for improved biomarkers, actively investigating new candidates, such as paraneoplastic Ma antigen 2 (PNMA2) which is detected in small intestine carcinoid tumors and used to assess the risk of recurrence." (PMID 36903295, 2023).
cancer (26 papers, 2011 to 2026). A tumor composed of atypical neoplastic, often pleomorphic cells that invade other tissues. "Moreover, our analysis revealed cell-specific expressions, such as CARD11 in cancer cells, PNMA2 in proliferative cells, MAGEA3 in gland mucous cells, and KIT in chief cells." (PMID 38962317, 2024). "We found four paired lncRNA-mRNA exhibiting a substantially high SCNA frequency in cancers, including lncRNA FGD5-AS1 and PRKAR2A (KIRC, 44.2% and 44.4%), lncRNA TUG1 and CDC7 (LUAD, 25.9% and 23.6%), lncRNA TUG1 and DSC2 (LUAD, 25.9% and 26.1%) and lncRNA SNHG7 and PNMA2 (LUAD, 25.4% and 31.1%)." (PMID 32846981, 2020).
tumor (19 papers, 2008 to 2026). "Positively stained tissues showed PNMA2 immunoreactivity from faint to moderate granular accumulation of immunostaining product confined to the cytoplasm of most tumor cells." (PMID 21209860, 2010).
PNMA2 also shares sentences with these, for which no sentence is quoted: autoimmune encephalitis (10 papers); testicular cancer (10); small cell lung carcinoma (8); glioblastoma (7); infection (5); Autoimmunity (4); breast carcinoma (4); lung carcinoma (4); melanoma (4); non-small cell lung carcinoma (4); testicular tumors (4); thymoma (4); neuroblastoma (3); Sleep disturbance (3); Ataxia (2); dementia (2); herpes simplex encephalitis (2); Hodgkins lymphoma (2); leukemia (2); lymph node metastasis (2); myasthenia gravis (2); neuroendocrine tumor (2); Nystagmus (2); ovarian carcinoma (2); Parkinsonism (2); Sjögren syndrome (2); acute myeloid leukemia (1); adenocarcinoma (1); Alzheimer disease (1); Anxiety (1).
A further 65 diseases each share a sentence with PNMA2 in 1 paper.